EGFR (epidermal growth factor receptor)
Diseases named in the same sentence as EGFR in open-access papers (continued):
Sharing a sentence is not in itself a finding about the gene and the disease.
glioblastoma (continued). "Epidermal growth factor receptor gene (EGFR) alteration is a common feature in most of glioblastoma multiforme (GBM)." (PMID 24352766, 2014). "However, most glioblastoma patients respond poorly to anti-EGFR therapy." (PMID 24650032, 2014). "In particular, EGFR and c-Met are coexpressed in GBM, and dysregulated EGFR signaling in glioblastoma increases HGF binding to c-Met promoting cell invasion." (PMID 24709958, 2014). "Reports in colorectal cancer suggest BRAF-mutant tumors may escape inhibition by amplifying receptor tyrosine kinases, such as epidermal growth factor receptor (EGFR), and EGFR amplification and fusion are common alterations found in adult glioblastoma multiforme lesions." (PMID 24725538, 2014). "As such, these tumors may be less sensitive to EGFR inhibitors relative to G-CIMP- glioblastomas." (PMID 25277177, 2014). "For example, immobilized anti-EGFR RNA aptamer on a chemically modified glass surface can determine the presence and/or extent of GBM (glioblastoma) tumor cells." (PMID 25050359, 2014). "Here we apply our integrated approach to prioritize experiments for probing the signaling pathways downstream of a mutant epidermal growth factor receptor (EGFR) in glioblastoma multiforme (GBM)." (PMID 23408876, 2013). "In addition, miR-7 down-regulates EGFR mRNA and protein expression in cancer cell lines (lung, breast, and glioblastoma) and the AKT pathway inhibiting schwannoma cell growth and inducing cell cycle arrest and cell death, which suggests a negative regulatory mechanism acting on the MAPK pathway." (PMID 23724959, 2013). "Our study demonstrated that miR-219-5p targeted EGFR in glioma cells and the downregulation of miR-219-5p in the glioblastoma patient samples could be attributed to the increased levels of EGFR, thus increasing the activity of the RTK pathway and promoting tumor growth." (PMID 23690991, 2013). "Additionally, the EGFR promoter is hypermethylated in both low-and high-grade glioblastoma." (PMID 23776563, 2013). "It is evident that glioblastomas exhibit molecular heterogeneity involving EGFRvIII and PTEN mutations, increased AKT activation, or MGMT promoter methylation that may differentiate the efficiency of EGFR-AKT-mTOR cascade targeting among patients." (PMID 22530122, 2012). "Deletion of NFKBIA (encoding nuclear factor of κ-light polypeptide gene enhancer in B-cells inhibitor-α), an inhibitor of the EGFR-signaling pathway, promotes tumorigenesis in glioblastomas that do not have alterations of EGFR and is associated with a poor prognosis." (PMID 22553975, 2012). "Moreover, MARCKS plays a critical role in EGFR-induced invasion of glioblastoma cells." (PMID 22745766, 2012). "EGFR/EGFRvIII gene amplification is frequent in glioblastoma multiforme (GBM), the most common and deadliest brain cancer in adults." (PMID 21388543, 2011). "In addition, the discovery of the function of EFEMP1 as a tumor suppressor that modulates EGFR suggests a need to further investigate EFEMP1 as a potential predictive marker for anti-EGFR therapies of cancer, including glioblastoma, lung, breast, prostate, and liver cancers." (PMID 21955618, 2011). "The EGFRvIII mutant is a common oncogenic mutant co-expressed with wild-type EGFR in glioblastoma (GBM)." (PMID 21917185, 2011). "EGFR gene amplification or overexpression is a particularly striking feature of glioblastoma (GBM), observed in approximately 40% of tumors." (PMID 21575270, 2011).
glioblastoma (continued). "Besides direct VEGF or VEGFR2 inhibition for glioblastoma, clinical studies are being conducted or planned with agents targeting further downstream or alternative pathways frequently altered in brain tumors, including the mTOR/Akt and EGFR pathways." (PMID 21771332, 2011). "Amplification of the epidermal growth factor receptor locus is found in approximately 40% of primary GBMs but is rarely found in secondary glioblastomas; mutations of the PTEN gene are observed in 45% of primary GBMs and to a lesser extent in secondary glioblastomas." (PMID 20339586, 2010). "A Phase I trial is currently investigating the combination with erlotinib (an EGFR inhibitor), while Phase I/II trials to assess the use of a dasatinib/radiotherapy/temozolomide regime in conjunction with adjuvant dasatinib and temozolomide for newly diagnosed glioblastoma are about to be launched." (PMID 20652056, 2010). "Approximately, 50–75% of glioblastoma's (GBM's) exhibit EGFR gene amplification and trisomy/polysomy of chromosome 7 in addition to other chromosomal aberrations." (PMID 19898616, 2009). "In brain tumor specimens, expression of FABP7 in primary glioblastoma was inversely associated with survival in a specific age group and nuclear but not cytoplasmic FABP7 protein was associated with EGFR overexpression and shorter survival in glioblastoma patients." (PMID 19014610, 2008). "The epidermal growth factor receptor (EGFR) is over expressed in approximately 50–60% of glioblastoma (GBM) tumors, and the most common EGFR mutant, EGFRvIII, is expressed in 24–67% of cases." (PMID 16236164, 2005). "EGFR alterations, particularly amplifications, generally predict worse survival in astrocytomas and glioblastomas, while PTEN alterations (mutations or deletions) are linked to poor prognosis specifically in GBM." (PMID 41249878, 2026). "This platform enabled the development of oHSVs targeting EGFR, PSMA, and glioblastoma-specific EGFRvIII." (PMID 41403403, 2026). "Since EGFR is a key regulator in glioblastoma growth and upstream of both the MAPK and PI3K/AKT pathways, inhibitors targeting EGFR and ERK1/2 were selected to assess their interactions with LSD1 inhibition." (PMID 41497449, 2025). "It has been used in trials alongside epidermal growth factor receptor (EGFR) inhibitors and other immune checkpoint inhibitors, with some success in treating glioblastoma." (PMID 40243541, 2025). "In this study, the objective was to investigate the uptake of EGFR-selective aptamers - Gol1 and GR20, labeled with a radioactive 4-[18F]- fluorobenzylazide, in laboratory animals with a grafted rat tissue 101.8 glioblastoma model." (PMID 41473440, 2025). "Radiation resistance in glioblastoma (GBM) poses a persistent clinical hurdle, driven in part by hyperactivated EGFR and NF-κB signaling." (PMID 41120287, 2025). "In glioblastoma patients receiving EGFR TKI targeted therapy, tumor cells acquire EGFR TKI resistance by eliminating EGFRvIII ecDNA, and EGFRvIII ecDNA reappear after drug withdrawal." (PMID 41030947, 2025). "A recent study showed that targeting the EGFR/AKT and mevalonate pathways enhanced the antitumor effect of temozolomide in glioblastoma cells and animal models." (PMID 40075591, 2025). "Subsequently, researchers found that FPR expressed in glioblastoma cell lines promotes the production of VEGF by tumor cells and transduces signals that selectively induce the phosphorylation of the epidermal growth factor receptor (EGFR)." (PMID 40733247, 2025). "Our study identifies EGFR alterations, specifically EGFR amplification, as a significant predictor of REP in glioblastoma." (PMID 41212363, 2025). "In glioblastoma, GBP1’s EGFR-driven role marks it as a malignancy indicator, detectable near the plasma membrane or in cytoplasmic granules via immunohistochemistry, providing a reliable prognostic tool." (PMID 40564939, 2025).
glioblastoma (continued). "In this study, our aim was to examine the relative expression and prognostic significance of all members of the HER family, the type III EGFR mutant (EGFRvIII), and the putative stem cell markers CD44 and CD109 in patients with glioblastoma." (PMID 40227788, 2025). "The phosphorylation status of Cx43 in glioblastoma multiforme (GBM) may affect the activity of the downstream signaling pathway of EGFR by modulating its binding ability to Akt/ERK." (PMID 40416989, 2025). "Many glioblastomas display subclonal amplifications of receptor tyrosine kinases (RTKs) such as MET, EGFR, and PDGFRA within the same tumor." (PMID 40723205, 2025). "Isocitrate dehydrogenase (IDH)-wildtype adult-type diffuse astrocytic tumors with EGFR amplification, TERT promoter (TERTp) mutations, or combined gain of chromosome 7 and loss of chromosome 10 can be classified as glioblastomas (GBM), even with low histological grades." (PMID 40786409, 2025). "In glioblastoma, GBP1 acts as an EGFR-induced effector, enhancing tumor growth in vivo—an effect absent in vitro, suggesting reliance on stromal or immune interactions within the brain tumor microenvironment (TME)." (PMID 40564939, 2025). "The activation of EGFR was shown to be accompanied by the upregulation of CD44 expression and the enhancement of the migratory and invasive capabilities of glioblastoma cells." (PMID 40227788, 2025). "C-E-Cad activates the EGFR signaling pathway by binding to the EGFR CR2 domain, leading to glioblastoma tumorigenesis." (PMID 41208886, 2025). "It has been reported that METTL3 enhances the translation of oncogenes such as epidermal growth factor receptor (EGFR), which is a key oncogene frequently amplified in glioblastomas." (PMID 41321637, 2025). "Alterations in DNA methylation and histone modifications modulate the activity of key pathways such as EGFR, PI3K/AKT, Notch, and Wnt, thereby regulating the behavior of tumor cells and glioblastoma stem cells (GSCs)." (PMID 41465586, 2025). "Overexpression of the epidermal growth factor receptor (EGFR) in primary tumors of prostate cancer and in high-grade gliomas, such as glioblastoma, often correlates with a poorer prognosis." (PMID 39860082, 2025). "Moreover, C/EBPβ upregulated in EGFR-overexpressed GBM cells is inversely correlated with the survival rates of glioblastoma patients." (PMID 41009025, 2025). "Elevated soluble EGFR (sEGFR) levels have been reported in glioblastoma and CRC, where they correlate with altered responses to anti-EGFR antibodies." (PMID 41465349, 2025). "In gliomas, especially glioblastoma (GBM), the EGFR/MAPK signaling pathway is widely considered to be one of the key axes driving tumor occurrence and progression." (PMID 40630952, 2025). "In conclusion, this retrospective study suggests a potential prognostic value of EGFR amplification and MGMT promoter methylation in IDH-wild-type glioblastoma treated with standard chemoradiotherapy." (PMID 40722305, 2025). "Interactions between the EGFR and CD44 were reported to play a significant role in the pathology of glioblastoma." (PMID 40227788, 2025). "These insights underscore the prognostic importance of EGFR and MGMT status in shaping glioblastoma treatment outcomes and recurrence dynamics." (PMID 40722305, 2025). "In glioblastoma models involving mice and pigs, FUS has been shown to increase ctDNA levels, enabling improved sensitivity of biomarkers such as EGFR and TERT as well as enhanced detection of green fluorescent protein (eGFP)." (PMID 39796751, 2025). "Using the MTS assay method, we evaluated changes in the proliferative potential of the human glioblastoma culture cells G01 and BU881, which are characterized by different expression levels of the two target receptors, EGFR and EGFRvIII." (PMID 39940838, 2025).
glioblastoma (continued). "Testing IDH wild type gliomas if bearing EGFR amplification, TERT promoter region mutation, or chromosome 7 gain and chromosome 10 loss genetic alterations versus other gliomas, could be similarly used to classify glioblastoma (WHO classification 5th edition 2021) samples." (PMID 39578301, 2025). "The interplay of these effects transforms a “cold” TME into a “hot” TME with increased immune cells, providing a rationale to combine OV, or specifically OV-IL-15C, with EGFR-CAR-NK cells, for targeting heterogeneous glioblastoma." (PMID 40650066, 2025). "The interaction between EGFR and HSP70 in glioblastoma is complex and influential, offering therapeutic opportunities alongside challenges." (PMID 40313865, 2025). "RTKs including EGFR, VEGFR, PDGFR, MET, and AXL regulate essential activities such as cell proliferation, survival, invasion, and angiogenesis, enhancing glioblastoma’s resistance to standard treatments." (PMID 40332008, 2025). "designed an anti-EGFR vIII CAR-T with autocrine anti-EGFR BiTE and demonstrated its ability to eradicate heterogeneous tumor cells in a glioblastoma mouse model." (PMID 40469307, 2025). "Genomic alterations resulting in EGFRvIII expression have been reported in glioblastoma, promoting downstream MAPK and PI3K/Akt signaling, and display responsiveness to epidermal growth factor receptor (EGFR) inhibition with gefitinib or lapatinib." (PMID 39919177, 2025). "According to the WHO Classification 2021, Glioblastoma is categorized as a grade IV tumor, with specific molecular alterations (IDH‐wildtype, TERT, EGFR, chromosome +7/−1)." (PMID 40498413, 2025). "For example, studies demonstrated that miR-7-5p inhibited EGFR mRNA and protein expression and downstream AKT and ERK1/2 activity in head and neck, breast, lung, and prostate cancers, as well as in glioblastoma multiforme." (PMID 38393538, 2025). "The four RTK subgroups, G1/EGFR, G2/FGFR3, G5/PDGFRA and G6/Multi-RTK, totaled over 50% of the cases, underscoring the importance of RTK signaling for glioblastoma pathogenesis." (PMID 38254850, 2024). "Diffuse astrocytic tumours lacking the histological features of glioblastoma are designated molecular GBM (molGBM, WHO grade 4) if they exhibit specific molecular abnormalities, such as TERT promoter mutation, EGFR amplification, or chromosomal + 7/− 10 copy changes." (PMID 38890658, 2024). "Temozolomide’s antitumor effects, targeting the mevalonate and EGFR/AKT pathways, demonstrate significant clinical management of glioblastoma." (PMID 39484162, 2024). "The tumor-targeting domains of the bispecific antibodies were also functional, indicated by a strong binding of NKAB-EGFR and less pronounced binding of NKAB-ErbB2 to T98G glioblastoma cells, which express high levels of EGFR and more moderate levels of ErbB2." (PMID 38334638, 2024). "Due to promising results, the combination of EGFR and HDAC inhibition has been assessed in a phase I/II clinical trial in recurrent glioblastoma (NCT01110876)." (PMID 38183103, 2024). "In another study, it was found that when an EGFR inhibitor was combined with a histone deacetylase (HDAC) inhibitor, human glioblastoma cell viability and proliferation were reduced." (PMID 38396993, 2024). "However, in glioblastoma, EGFR receptor mutations are primarily intracellular and display active signaling but are conformationally inactive; hence, these traditional TKIs are not completely effective in targeting EGFR in glioblastoma." (PMID 39518074, 2024). "Various clinical trials are evaluating targeted therapies, such as EGFR inhibitors and EGFR-specific CAR-T cell therapies, to assess their efficacy in EGFR-amplified glioblastoma." (PMID 39767571, 2024).
glioblastoma (continued). "Another phase I clinical trial delivering bivalent (targeting EGFR and IL13Rα2) CAR T cells to six patients intrathecally showed efficacy with preliminary safety against recurrent glioblastoma." (PMID 39452154, 2024). "The signaling pathways of RTKs, including EGFR, PDGFR, and/or c-MET, are often modified throughout the pathogenesis of glioblastoma multiforme (GBM)." (PMID 38504984, 2024). "We observed diffuse astrocytic/glial proliferation with marked EGFR gene amplification in the four CDX (6638, 7220, 9447, DB) and PDX-P3, in line with the generation of glioblastoma in mice engrafted with human cytomegalovirus-infected astrocytes." (PMID 38553638, 2024). "A well-known target for peptide vaccines is the epidermal growth factor receptor (EGFR), which is a receptor tyrosine kinase that is highly expressed in glioblastoma." (PMID 38523646, 2024). "Rui Ma and his team designed an oHSV called OV-IL15C.They used OV-IL15C with frozen EGFR-CAR-NK cells to study them in vitro and multiple glioblastomas mouse models for monotherapy and combination therapy effects." (PMID 39046631, 2024). "Aberrant splicing to produce EGFR exons 2-7 skipping mRNA, and MET exon 14 skipping mRNA were identified in glioblastoma and pancreas carcinoma BM, respectively." (PMID 39087020, 2024). "Histologically, most of the tumors corresponded to glioblastoma IDH wild type (n = 43, 81.1%), 20 (41.6%) of which displayed an EGFR amplification." (PMID 39456559, 2024). "Members of the receptor tyrosine kinase gene family including EGFR, MET, PDGFRA, and FGFR3 have been known to be heavily involved in the initiation and progression of glioblastoma." (PMID 39087020, 2024). "In order to improve the anti-tumour activity of NK cells in immunotherapy, they produced an EGFR-CAR-NK cell, and finally obtained anti- glioblastomas effects in both in vivo and in vitro experiments in xenograft models." (PMID 39046631, 2024). "It has been documented that MSCs derived from human cord blood minimized the invasion and migration potential of glioblastoma cell lines by downregulating c-Myc/ERK, PI3K/AKT, and EGFR/c-Met pathways." (PMID 39768220, 2024). "Through functional enrichment analysis, we identified the following pathways MAPK, EGF/EGFR, Ras, EGFR, PI3K-AKT signaling, MAPK signaling, Glioblastoma signaling, pathways as a common target for miR-21, miR-374, and miR-126." (PMID 39348350, 2024). "In glioblastoma, most RTK driver alterations were CN gains/amplifications, accounted for by EGFR, PDGFRA, and to a lesser extent, MET." (PMID 38254850, 2024). "The molecular subgroup demographic analysis for the Combined glioblastoma cohort found a significantly higher patient age for the G7/Other and G6/Multi-RTK subgroups versus the G1/EGFR subgroup." (PMID 38254850, 2024). "The degree to which EGFR, PI3K, NFKβ, JAK-STAT, CK2, WNT, NOTCH, Hedgehog, and TGFβ are dependent on each other, and redundant with each other, in the context of glioblastoma therapeutics remains to be fully elucidated." (PMID 38672566, 2024).